ABCB1 (ATP binding cassette subfamily B member 1)
Diseases named in the same sentence as ABCB1 in open-access papers (continued):
Sharing a sentence is not in itself a finding about the gene and the disease.
ovarian carcinoma (continued). "Taken together our findings demonstrated that CYLD was a DDP sensitizer which may be as a new biomarker for ovarian cancer DDP resistance, the HER3 inhibitor and ABCB1 inhibitor combination greatly increased cisplatin treatment effect, and made DDP resistant OC cells to become sensitive cells." (PMID 40012003, 2025). "One of the earliest identified resistance mechanisms was the upregulation of the ABCB1 (MDR1, P-glycoprotein) drug efflux transporter, which reduces intracellular drug accumulation and has been observed in both PARPi- and platinum-resistant ovarian cancer cells." (PMID 40426953, 2025). "In an ovarian cancer model, treatment with estrogen also downregulated P-gp protein without amplification of ABCB1; however, they found that treatment with progesterone did increase ABCB1 RNA, and a combination treatment of estrogen and progesterone led to lower ABCB1 RNA and P-gp levels." (PMID 37686513, 2023). "Studies aiming to identify their role in ovarian cancer have shown that all of these three miRNAs mediate glutathione S-transferase-π (GST-π) and multidrug resistance protein 1 (MDR1) modulation via targeting ATP-binding cassette targeting sub-family B [MDR/TAP], member 1 (ABCB1)." (PMID 31936634, 2020). "In ovarian cancer, the most common mechanism for resistance to paclitaxel and other chemotherapeutic agents is overexpression of ATP-dependent membrane efflux pumps of the ABC transporter family, especially Multidrug Resistance Protein 1 (MDR1)/P-glycoprotein/ABCB1." (PMID 29599904, 2018). "The activation of the JNK pathway resulted in decreased ABCB1 gene expression through the binding of c-Jun, the transcription factor in the downstream of JNK pathway, to the promoter region of the ABCB1 gene in human ovarian cancer cell lines and lung cancer cell lines." (PMID 29061940, 2015). "We found no ABCB1 expression in any of the ovarian cancer cell lines (data not shown)." (PMID 24124770, 2013). "However, we did not observe ABCB1 expression in any of the ovarian cancer cell lines examined, neither in the absence nor presence of HA." (PMID 24124770, 2013). "Since ABCB1 expression is of uncertain clinical significance in ovarian cancers, including those resistant to taxanes, in this study we developed non-MDR-resistant variants by co-exposure of a panel of ovarian cancer cell lines to a taxane plus the P-gp inhibitor PSC." (PMID 28399108, 2017). "In cisplatin-resistant ovarian cancer cells (SKOV3, A2780), downregulation of caveolin-1 had no impact on total ABCB1 protein expression despite the increased apoptosis to cisplatin, a DNA damaging agent." (PMID 35582031, 2021). "For instance, ABCB1-expressing, but not ABCG2-positive, SP cells will be resistant to paclitaxel, an agent commonly used for ovarian cancer treatment." (PMID 25216521, 2014).
leukemia (118 papers, 1989 to 2026). A malignant (clonal) hematologic disorder, involving hematopoietic stem cells and characterized by the presence of primitive or atypical myeloid or lymphoid cells in the bone marrow and the blood. "Another synonymous variant of ABCB1, rs1128503, has also been linked to risk for leukaemia in individuals carrying the TT genotype." (PMID 36077209, 2022). "In leukemia, the product of ABCB1, P-glycoprotein (Pgp), is most commonly implicated in the development of drug resistance." (PMID 22823957, 2012). "Clinical insensitivity to anticancer agents is mainly attributed to an elevated expression of ABCB1, which is related to treatment failure associated with lower remission and survival rates in some types of cancer, including leukemias." (PMID 23259070, 2012). "We functionally confirmed these observations not only in the two representative AML cell lines KG1 and U937 but also in primary cells (AML#1 and AML#2) isolated from leukemia patients at the time of diagnosis based on their expression levels of ABCB1 and LSC-associated markers." (PMID 35628366, 2022). "To facilitate the understanding of the intractability of the ABCB1 coding regions to drug-induced mutations in these leukemia cells, we compared the exonic variant allele frequencies, an indicator of genomic stability, between ABCB1 and several representative transporter genes in human populations." (PMID 34541464, 2020). "Because ABCB1 was highly associated with CD34 and CD33 we postulated that ABCB1 may be a bystander effect inherent to a respective leukemia stem cell (LSC) phenotype." (PMID 31500210, 2019). "The Kaplan–Meier analysis of the survival time of patients with 23 different tumor types showed that ABCB1 expression is prognostically relevant for leukemia and multiple myeloma." (PMID 40723843, 2025). "In one study, a drug screen testing for active combinations with FK866 in primary leukemia cells identified cyclosporin A, a calcineurin inhibitor and a P-GP/ABCB1 inhibitor, as an enhancer of NAMPT inhibitor activity." (PMID 40342733, 2025). "Kaplan–Meier statistics of RNA sequencing data of tumor biopsies of TCGA database revealed that high ABCB1 expression was significantly correlated with worse survival times for leukemia, multiple myeloma, and hepatocellular carcinoma patients." (PMID 40723843, 2025). "It has been described that P-glycoprotein/ABCB1 is linked to worse survival prognosis, including leukemia, multiple myeloma, and hepatocellular carcinoma albeit with low patient numbers." (PMID 40723843, 2025). "SRI encodes Sorcin, a calcium-binding protein that has been associated with increased tumor aggressiveness and can induce ABCB1 expression in leukemia." (PMID 38163893, 2024). "We generated a Doxo-resistant leukemia cell line by overexpressing ABCB1 and tested its sensitivity to other anthracyclines." (PMID 38831402, 2024). "Using ChIP and vincristine-resistant K562 leukemia cells, it was established that β-catenin was bound to the ABCB1 promoter at a much higher frequency than in the K562 vincristine-sensitive cells." (PMID 37686513, 2023). "In 1985, the ABCB1 gene was cloned, and, using this cDNA as a probe, researchers were able to show that ABCB1 DNA was amplified in the vinblastine-resistant leukemia cell line CEM/VLB compared to its parental counterpart, CCRF-CEM." (PMID 37686513, 2023). "It was consistent with previous reports that apatinib increased the antitumour effect of doxorubicin in side population cells and ABCB1‐overexpressing leukaemia cells." (PMID 35315581, 2022). "In a previous study, human leukemia K562 cells expressing various levels of ABCB1 were used and cells expressing higher ABCB1 levels required higher concentrations of imatinib and nilotinib to achieve full reversal of drug efflux." (PMID 34572902, 2021).
leukemia (continued). "To do this, we used leukemia K562 cells with high and moderate expressions of ABCB1, K562/DoxDR3 and K562/DoxDR2, and ABCG2, K562/ABCG2CL10 and K562/ABCG2CL4, respectively." (PMID 33573093, 2021). "All together these data demonstrate that expression of the daunorubicin drug export pump ABCB1 is dynamically regulated in leukemia cells though the ATF4-bound E3 enhancer." (PMID 31770110, 2020). "Our analyses reveal the network of enhancers that controls intrinsic expression of ABCB1 in human leukemia cells; the gene is a direct target of the transcription factor ATF4, which is activated through a chemotherapy-induced cellular stress response." (PMID 31770110, 2020). "P-glycoprotein (P-gp, ABCB1 member of the ABC (ATP-binding cassette) transporter family) localized in leukemia cell plasma membranes is known to reduce cell sensitivity to a large but well-defined group of chemicals known as P-gp substrates." (PMID 32268491, 2020). "We found that ABCB1 expression of the leukemia bulk is related to its hematopoietic progenitor cell ABCB1 expression." (PMID 31500210, 2019). "In this study, we found midostaurin, a Food and Drug Administration (FDA)-approved anti-leukemia drug, can antagonize ATP-binding cassette subfamily B member 1 (ABCB1)-mediated MDR." (PMID 31275850, 2019). "It has been reported that ABCB1 intercellular transfer occurred in leukemia cells, osteosarcoma, neuroblastoma and breast adenocarcinoma cells." (PMID 31830995, 2019). "Although clinical evidence in leukemia patients is scarce, we consider that its use in this stage of treatment is beneficial only in patients with high levels of ABCB1 gene expression." (PMID 30176891, 2018). "A recent study demonstrated that transcription factor STAT3 was involved in the regulation of ABCB1 transcription by binding with its promoter region in leukemia cells." (PMID 27409663, 2016). "Previous studies on leukaemia cell lines have shown that ABT-737 is a substrate for ABCB1, therefore the pro-apoptotic activity of ABT-737 and obatoclax were tested on these 3 cell lines with and without the ABCB1 inhibitor VPL." (PMID 24887326, 2014). "ABCB1 also mediates resistance to the A3AR agonist 2‐Cl‐IB‐MECA in human leukemia cells." (PMID 40181576, 2025). "The frequent ABCG2 and ABCB1 co-expression on leukemia cells, with synergistic effects on drug efflux, may have a role in reducing the complete remission rate and in favoring early relapse." (PMID 38255216, 2024). "A potential explanation is suggested by our observation that exposure of leukemia cells with primed ABCB1 enhancers to daunorubicin leads to rapid and substantial upregulation of ABCB1, with escape of a leukemia cell subpopulation from the effects of drug efflux pump inhibition." (PMID 31770110, 2020). "Sorcin overexpression increases ABCB1 expression, determining increased drug resistance to several drugs, while sorcin silencing decreases expression of ABCB1, increasing cell death, in gastric cancer cells, lung tumor cells, nasopharyngeal carcinoma, cervical carcinoma cells, and leukemias." (PMID 32268494, 2020). "Thus, TCGA data provide a genetic basis that accounts for the genomic stability of the ABCB1 coding regions in our drug-resistant leukemia models." (PMID 34541464, 2020). "Our study in leukemia models revealed that ABCB1 coding regions are stable even under stringent drug selection, thus suggesting that a mutant P-gp may not be a major factor responsible for the unsuccessful modulation of clinical MDR." (PMID 34541464, 2020). "Thus, the ABCB1 promoter exhibits a network of physical contacts with nearby enhancers in drug-resistant K562 leukemia cells." (PMID 31770110, 2020). "In this study, our aims were to establish CsA-resistant leukemia models and to examine the presence or absence of ABCB1 exonic mutations in these models as well as in diverse types of human cancer samples including AMLs." (PMID 34541464, 2020).
leukemia (continued). "Because gene mutations play a significant role in conferring drug resistance, our original aim was to examine the presence or absence of ABCB1 exonic mutations in these drug-resistant leukemia models." (PMID 34541464, 2020). "Overexpression of ABCB1 was found in various carcinomas such as non-small cell lung cancer, breast cancer, gastric cancer, nasal NK/T cell lymphoma, T/NK-cell lymphomas, prostate cancer, ovarian carcinoma, and leukemia." (PMID 31801248, 2019). "What’s more, the MTT cytotoxicity assays showed that neratinib markedly sensitized primary leukemia blasts to doxurubin compared with the control group (P < 0.05), indicating neratinib may play a role in the reversal of ABCB1-mediated MDR phenotype." (PMID 29455646, 2018). "Firstly, they obtained clinical samples of ABCB1-overexpressing leukemia cells from patients." (PMID 29455646, 2018). "ABCB1 is related to resistance phenotype in some leukemias and it has been studied in advanced CML." (PMID 23259070, 2012). "Sorcin overexpression leads to increased ABCB1 levels, ultimately enhancing drug resistance in various cancer cell lines, including those from gastric cancer, lung tumors, nasopharyngeal carcinoma, cervical carcinoma, and leukemias, while sorcin silencing reduces ABCB1 expression." (PMID 39199583, 2024). "This pathway may be differentially active in ABCB1-positive and ABCB1-negative leukemia cells." (PMID 34298843, 2021). "Thus daunorubicin- and stress-induced acute induction of ABCB1 can overcome pharmacologic inhibition of ABCB1, leading to leukemia cell survival, and this can, at least in part, be mitigated by concomitant treatment of cells with inhibitors of stress signaling." (PMID 31770110, 2020). "This hypothesis was based on the fact that ABCB1 is expressed in early primitive normal hematopoietic stem cells and can be over-expressed in leukemic stem cells, which would aid in maintenance of leukemia." (PMID 22458888, 2012). "For example, upregulation of miR-138 significantly downregulates ABCB1 expression, thereby reversing Adriamycin resistance in the MDR HL-60/VCR leukemia cell line." (PMID 40678416, 2025). "Ribociclib, a CDK4/6 inhibitor approved for the treatment of locally advanced/ metastatic breast cancer, revealed ABCB1 and ABCG2-mediated daunorubicin and mitoxantrone efflux inhibition in AML cell lines and in CD4+/Flt3-WT leukemia cells." (PMID 38255216, 2024). "HSS administration reduces sorcin, BCR/ABL, and ABCB1 expression in mouse models and results in increased apoptosis in MDR leukemia cells." (PMID 39199583, 2024). "In contrast, the U937 monocytic differentiated leukemia cell line exhibited a downregulation of LSC markers and a decrease in ABCB1 gene expression." (PMID 35628366, 2022). "Based on the real-time PCR assay, 5 days of incubation with ATRA (10 μM), kaempferol, and EGCG (100 μM) decreased the expressions of ABCB1 and ABCC1 genes in leukemia HL60 cells (p<0.001)." (PMID 34290963, 2021). "Specifically, miR-138 re-expression was responsible for the downregulation of ABCB1 (Pgp/MDR1), subsequently leading to increased apoptosis and reversal of Adriamycin resistance in MDR leukemia cells." (PMID 35582270, 2019). "In particular, ABC subfamily B-member 1 (ABCB1) also known as permeability glycoprotein and multi-drug resistance (P-gp or MDR1), has been extensively studied in solid cancers and leukemia." (PMID 31500210, 2019). "The other genes affected by MPs in cancer cells are ABCB1 and ABCG2 in Leukemia." (PMID 41378310, 2025). "High levels of ABCB4 expression have been reported in different leukaemias, even without co-expression with ABCB1." (PMID 36901890, 2023). "In leukaemia cells, daunorubicin accumulation is dependent on transporter inhibition with Cyclosporin A, indicating that ABCB4 is able to remove ABCB1 substrates from cancer cells and may play an active role in drug resistance." (PMID 36901890, 2023).
leukemia (continued). "Among the ABC transporter members, ATP Binding Cassette Subfamily B Member 1 (MDR1) and ATP Binding Cassette Subfamily C Member 1 (MRP1) genes, located on chromosomes 7 and 6, respectively, have shown the maximum relation with drug resistance in leukemia." (PMID 34181359, 2021). "Furthermore, it is well known that ABCB1 and ABCG2 are expressed in a drug-resistant subpopulation of leukemia stem cells (CD34+ CD38−)." (PMID 29316665, 2018). "In a previous study, we showed that 3β-acetyl tormentic acid (3ATA), a triterpene isolated from Cecropia lyratiloba, is able to induce apoptosis in an MDR leukemia cell line overexpressing P-gp/ABCB1 without interfering with P-gp/ABCB1 expression or activity." (PMID 22837662, 2012). "In addition, although high methylation of the ABCB1 promoter in MLL+ children inhibits its mRNA expression, decitabine can restore ABCB1 expression through demethylation and enhance the sensitivity of leukemia cells to chemotherapy drugs (decreased IC50)." (PMID 41195225, 2025). "Moreover, Apatinib could reverse ABCB1- and ABCG2-mediated multidrug resistance in solid tumors as well as in leukemia cell lines, thereby enhancing the efficacy of chemotherapeutic agents." (PMID 29490645, 2018). "Thus, targeting both ABCB1 and MCL‐1 may help overcome drug resistance in human leukemia." (PMID 30891950, 2019).